COL4A1 (collagen type IV alpha 1 chain)
Diseases named in the same sentence as COL4A1 in open-access papers (continued):
Sharing a sentence is not in itself a finding about the gene and the disease.
diabetes (9 papers, 2014 to 2024). "COL4A1 is also associated with obesity, one of the risk factors of diabetes." (PMID 33304382, 2020). "Moreover, COL4A1 in mesangial cells, the expression of which was increased in diabetes, acted on ITGB8 in glomerular endothelial cells." (PMID 34222276, 2021). "Based on existing evidence, miR-133a overexpression has prevented myocardial fibrotic event in both AngII-related hypertension and diabetes, even though the effector proteins were different in diabetes (fibronectin and COL4A1) and AngII-related hypertension (COL1A1)." (PMID 33569393, 2020). "In addition, our studies found that TSP1 targets included: TAGLN, a regulator of angiogenesis, LOXL4, a contributor to the vascular permeability in diabetes, types of collagen (COL4A1 and COL8A1) that influence angiogenesis plus THSB1 an inhibitor of angiogenesis." (PMID 36949528, 2023). "We further examined the expressions of several extracellular matrix(ECM) genes, COL1A1, COL4A1, and FN1, because the gene set enrichment analysis indicated enrichment of ECM deposition by MECs in diabetes." (PMID 39739865, 2024). "The observed increases in COL4A1, FN1 and phosphorylation of both ERK1/2 and SMAD-2 were prevented when miR-133a was overexpressed in the heart in diabetes." (PMID 24428157, 2014). "In our current study, we show that p300 mRNA levels increase with diabetes and this increase was correlated with an increase in mRNA levels of fibrosis inducers: EDN1, AGT, CTGF and TGF-β1, and ECM genes, e.g. COL4A1 and FN1." (PMID 24428157, 2014).
glioblastoma (9 papers, 2009 to 2025). The most malignant astrocytic tumor (WHO grade IV). "Here, we report a Japanese family with a novel COL4A1 variant, including a patient with recurrent epistaxis and glioblastoma." (PMID 33990551, 2021). "TME rearrangements in OS have been correlated with chemotherapy-resistant phenotypes, whereas a survival gene signature based on the expression of collagen genes Col3a1, Col4a1, and Col5a2 is correlated with glioblastoma and pancreatic cancer aggressiveness." (PMID 36831562, 2023). "TOP2A, COL4A1 and PXDN were significantly upregulated and ANK3, ARRB1 and ANO4 markedly downregulated in glioblastoma compared to controls." (PMID 32962742, 2020).
renal fibrosis (9 papers, 2018 to 2025). A final common manifestation of a wide variety of chronic kidney diseases characterized by glomerulosclerosis and tubulointerstitial fibrosis. "It is linked with abnormal activation of protein kinase C (PKC), elevation in expression levels of TGF-β1 and COL4A1 that enhances ECM deposition which causes renal fibrosis in RPTECs." (PMID 30496316, 2018). "scRNA-seq revealed that empagliflozin modulated the TGF-β signaling pathway, inhibited intercellular communication, and reduced the expression of fibrotic genes such as Col4a1 or Fn1 that are associated with miR-192-mediated TGF-beta/SMAD3-driven renal fibrosis." (PMID 41303298, 2025). "Col4a1 encodes type IV collagen, one of the main components of the ECM, and its role in renal fibrosis is self-evident." (PMID 39351084, 2024). "As described ahead, let-7c from MSC-EVs ameliorated renal fibrosis in UUO model with the downregulation of Col4a1, MMP-9, TGF-β1, and TGFBR1." (PMID 31979395, 2020). "As described ahead, the transfer of let-7c from MSC-EVs ameliorated renal fibrosis in UUO model through the downregulation of Col4a1, MMP-9, TGF-β1, and TGFBR1." (PMID 31979395, 2020). "In this study, MPs increased the levels of Cd-mediated autophagy marker LC3-II and the autophagy early proteins ATG5, Beclin-1, and ATG7 and increased the levels of the renal fibrosis marker proteins α-SMA, TGF-β1, and COL4A1." (PMID 36430889, 2022). "Our results indicate that renal fibrosis and RAS‐related genes (Fn, a‐SMA, Col1a1 and Col4a1) are increased at mRNA and protein expression levels in 5‐month‐old miR‐TKO mice." (PMID 34197043, 2021). "Meanwhile, renal fibrosis biomarkers (TGF-β1 and COL4A1) were tested using qRT-PCR and western blot assays." (PMID 31885559, 2019). "Meanwhile, renal fibrosis biomarkers (TGF-β1 and COL4A1) were tested using qRT-PCR and western blots." (PMID 31885559, 2019). "In addition, we observed that renal fibrosis biomarkers TGF-β1 and COL4A1 were greatly induced in db/db mice." (PMID 31885559, 2019).
atherosclerosis (8 papers, 2013 to 2025). A disease characterized by the build-up of fatty material and calcium deposition in the arterial wall resulting in partial or complete occlusion of the arterial lumen. "Perhaps the effects of COL4A1/COL4A2 variation occur early in development of atherosclerosis, setting the stage for effects of other genetic variants in subsequent phases of atherogenesis." (PMID 28642624, 2017). "Many of the genes identified are implicated in the regulation of SMC plasticity during atherosclerosis, including PDGFD, COL4A1/2, CDKN2B and CDKN2A/p19ARF." (PMID 23874238, 2013). "Additionally, a cell population co-expressing contractile genes with key ECM genes (Col1a1, Mgp, Eln, Fn1, Col4a1, and Col8a1) and Notch3, mapped together with the fcVSMC population from the atherosclerosis dataset (I-cluster 6)." (PMID 40577585, 2025). "Another large study evaluating 12 SNPs in RA patients, identified novel associations between subclinical atherosclerosis and variants in SLC17A2 (rs17526722), PPCDC (rs1867148), COL4A1 (rs496916) and SLCA13 (rs515291) genes, that may constitute new candidate risk loci for CVD in RA89." (PMID 35680906, 2022). "Therefore, the presence of circular RNA derived from this COL4A1 gene with potentially high stability in the circulation may be considered a promising biomarker candidate, applicable, for example, in atherosclerosis or other diseases in which angiogenesis disorders predominate." (PMID 37373172, 2023). "An unannotated disease-specific cell cluster (A-cluster 6) co-expressed contractile VSMC markers (Myh11, Acta2, and Cnn1) with several atherosclerosis-induced ECM genes (Col1a1, Mgp, Eln, Fn1, Col4a1, and Col8a1) and had reduced levels of Ly6a, Vcam1, and Tnfrsf11b compared to imVSMCs." (PMID 40577585, 2025). "In atherosclerosis, ECs communicated extensively with pericyte cells and SMCs through LAMININ (LAMA5-(ITGA1+ITGB1), LAMA5-(ITGA7+ITGB1), LAMB2-(ITGA6+ITGB4), LAMB2-(ITGA6+ITGB1)) and COLLAGEN (COL4A1-(ITGA1+ITGB1), COL4A2-(ITGA1+ITGB1)) pathways." (PMID 40225569, 2025).
cataract (8 papers, 2014 to 2026). Partial or complete opacity of the crystalline lens of one or both eyes that decreases visual acuity and eventually results in blindness. "In contrast, lens-specific expression of the conditional Col4a1 mutant allele led to cataracts, mild ASD and optic nerve hypoplasia, and age-related intraocular pressure dysregulation and optic nerve damage." (PMID 28237965, 2017). "In this case, multiple intracranial hemorrhages experienced during the patient’s course of birth and the presence of bilateral congenital cataracts led us to perform molecular testing to identify the COL4A1/A2 variant, and we diagnosed the patient with a COL4A1-related disorder." (PMID 35688819, 2022). "In the eye, Col4a1 mutations can lead to ASD encompassing corneal clouding, cataracts, iris hypoplasia and buphthalmos (enlargement of the anterior chamber) on slit lamp examination." (PMID 30351356, 2019). "Extra‐CNS involvement is also common in COL4A1 patients, featuring ocular anomalies (e.g., cataracts, anterior segment dysgenesis, retinal vascular tortuosity), intracranial calcifications, and myopathy mimicking congenital muscular dystrophy or Walker‐Warburg syndrome." (PMID 41499643, 2026). "The patient was the first child of nonconsanguineous parents with no family history of cerebral hemorrhages, seizures, cataracts, or other diseases associated with COL4A1/A2-related disorders." (PMID 35688819, 2022). "In addition, lens methylation profiles at cataract-related loci include Chmp4b, Col4a1–Col4a2, and Lss may help studies of aging human lenses and formation of cataracts." (PMID 36698218, 2023). "In contrast, ubiquitous conditional mutants (ActbCre;Col4a1+/Flex41) displayed the full ASD phenotypic spectrum, including dilated pupils, pigment dispersion, torturous and dilated iris vasculature, cataracts and enlarged anterior chambers." (PMID 28237965, 2017). "Slit lamp biomicroscopy of MLR10Cre;Col4a1+/Flex41 mice revealed the presence of cataracts but no anterior chamber enlargement." (PMID 28237965, 2017).
Gould syndrome (8 papers, 2021 to 2025). "In this study, we used five different Col4a1 mutant mouse strains that recapitulate the clinical spectrum of cerebrovascular manifestations associated with Gould syndrome." (PMID 41311701, 2025). "We introduced a heterozygous COL4A1 G755R mutation, which causes Gould syndrome, into a human microvascular brain endothelial cell line (HBEC) via CRISPR to measure basal Ca2+ levels and in response to acetylcholine." (PMID 39216230, 2024). "Previous studies showed that mutations in these genes cause a rare genetic form of CSVD as part of COL4A1-Syndrome (Gould Syndrome)." (PMID 39216230, 2024). "Missense mutations in COL4A1/COL4A2 cause early-onset CSVD with ICH in COL4A1 (Gould) Syndrome, while rare missense variants and common non-coding variants have also emerged as risk factors." (PMID 39216230, 2024). "Of the 49 respondents who further specified, 32 (65%) suggested genetic testing for DADA2 (CECR1 mutations), 5 suggested genetic testing for mutations in COL4A1 (Gould syndrome)." (PMID 34712632, 2021). "Gould syndrome is a highly variable multisystem disorder caused by COL4A1 and COL4A2 mutations, whose clinical presentation can vary widely between and within families ranging from asymptomatic COL4A1/COL4A2 mutation carriers to severely disabled individuals (Guey and Hervé, 2022)." (PMID 41311701, 2025). "Those two cases suggest that Col4a1+/G1038S mice may serve as an ideal pre-clinical platform to study the evolution of various radiological phenotypes of Gould syndrome, although a larger sample size is needed for a more comprehensive phenotypic description of other COL4A1 and COLA2 mutations." (PMID 41311701, 2025). "We used 5 Col4a1 mutant strains that well mimic the disease spectrum observed in individuals with Gould syndrome." (PMID 41311701, 2025). "Rare, dominant, coding mutations of COL4A1 and COL4A2 cause monogenic cerebrovascular disease as part of a highly variable multisystem disorder named Gould syndrome." (PMID 41311701, 2025). "To investigate how allelic heterogeneity influences cerebrovascular phenotypes, we examined five Col4a1 mutant mouse strains that collectively model the clinical spectrum of Gould syndrome." (PMID 41311701, 2025). "Previously, we successfully demonstrated that Col4a1 and Col4a2 mutant mice can recapitulate pathophysiological hallmarks of Gould syndrome, including ICH, whose severity was modulated by allelic heterogeneity." (PMID 41311701, 2025). "Murine models of Col4a1 and Col4a2 mutations faithfully replicate Gould syndrome and allelic heterogeneity was shown to modulate the severity of ICH in an allelic series of Col4a1 and Col4a2 mutant mice." (PMID 41311701, 2025). "COL4A1 and COL4A2 mutations cause Gould syndrome, a multisystem disorder mainly associated with cerebrovascular, ocular, renal, and muscular defects with variable disease onset, penetrance, and severity." (PMID 38717426, 2024). "Although the pathogenic mechanisms contributing to Gould syndrome are largely unknown, we recently reported that elevated transforming growth factor beta (TGFβ) signaling contributes to ocular and central nervous system vascular pathologies in Col4a1 mutant mice." (PMID 38717426, 2024). "Accordingly, semi-dominant COL4A1 and COL4A2 mutations cause Gould syndrome characterized primary by cerebrovascular manifestation in which TGF-β signaling is overactivated." (PMID 38980840, 2024). "This provides evidence that in late-onset sporadic CSVD coding variants do not affect collagen IV secretion, in contrast to COL4A1/COL4A2 mutations in early-onset familial Gould syndrome." (PMID 39216230, 2024). "BM defects, collagen IV misfolding with ER retention and ER stress can occur due to COL4A1/COL4A2 mutations, 10, 11 but the molecular cross-talk and relative contribution of these upstream molecular insults to the pathologies in Gould syndrome remains unknown." (PMID 39216230, 2024).
Gould syndrome (continued). "Consistent with their ubiquitous expression pattern, mutations in COL4A1 and COL4A2 cause a clinically heterogenous multisystem disorder characterized by cerebrovascular, ocular, renal, and muscular manifestations that are collectively referred to as Gould syndrome." (PMID 38717426, 2024). "No glycine mutations, equivalent to the Col4a1+/SVC mutation and the major cause of early-onset CSVD in Gould-syndrome, were identified in sporadic late-onset CSVD with ICH." (PMID 39216230, 2024). "Furthermore, since perinatal cerebral hemorrhage is a cardinal feature of Gould syndrome, we performed a genetic screen for PLOD3 variants in a fetal stroke cohort that was negative for COL4A1 and COL4A2 pathogenic variants." (PMID 36403858, 2022).
ischemic stroke (8 papers, 2018 to 2023). A stroke disorder caused by obstruction of blood flow to the brain, due to thrombotic (local blood clot formation) or embolic (due to a blood clot or other material traveling from another site) event. "Glycine missense mutations in COL4A1 may predispose to cerebral haemorrhage, whereas mutations upregulating COL4A1 gene expression are associated with ischaemic strokes." (PMID 36564356, 2023).
melanoma (8 papers, 2007 to 2025). A malignant, usually aggressive tumor composed of atypical, neoplastic melanocytes. "As it is not clear which cell types in TME mainly express COL4A1, we next analyzed COL4A1 expression levels in individual cells by “Study: Melanoma intra-tumor heterogeneity” through a Single Cell Portal." (PMID 35455650, 2022). "Those that effect a change in cell-cell cohesiveness (e.g. VIM, SPARC, COL4A1, and the integrins, ITGA4 and ITGAV), and have been shown to be over expressed in human or mouse melanoma samples, are each associated with one or more UV-miRNAs." (PMID 27149382, 2016). "A recent study showed that the knockdown of COL4A1 could reduce mouse melanoma cell motility and decrease lung metastasis in vivo." (PMID 27391030, 2016).
pulmonary fibrosis (8 papers, 2019 to 2025). Chronic progressive interstitial lung disorder characterized by the replacement of the lung tissue by connective tissue, leading to progressive dyspnea, respiratory failure, or right heart failure. "Given the contradictory role of type IV collagen in pulmonary fibrosis development, we next questioned how deeply Col4a1 and Col4a2 are associated with a regulation of fibrosis-related processes." (PMID 35625754, 2022). "Pirfenidone, used as treatment for pulmonary fibrosis, proved to be effective preventing an increase in COL4A1 and COL1A1 during OCT culture." (PMID 40104066, 2025). "We were particularly interested in the ECM associated genes and selected COL4A1, POSTN, MMP1 and MMP3 since they have been previously shown to be associated with pulmonary fibrosis." (PMID 33905434, 2021). "One of these, COL4A1 is considered a target of miR-29 in pulmonary fibrosis." (PMID 38203636, 2023). "Comparison of interactome of Col4a1 and Col4a2 with interactome of Col1a1, a key molecular determinant of pulmonary fibrosis, revealed their significant similarity—approximately 77% of partner genes of Col4a1 and Col4a2 retrieved from STRING database were found to be first neighbors of Col1a1." (PMID 35625754, 2022). "Moreover, few studies have explored the role of Col4a1 and Col4a2 in pulmonary fibrosis via TGF-β pathway modulation." (PMID 35625754, 2022). "The validation of genes related to non-allergic bleomycin-induced pulmonary fibrosis on asthmatic/fibrotic lungs allowed us to identify new universal genes (Col4a1 and Col4a2) associated with the development of lung fibrosis regardless of its etiology." (PMID 35625754, 2022). "A similar population of α-SMA positive cells expressing collagenous matrisome genes COL4A1 and COL4A2 were discovered in idiopathic pulmonary fibrosis (IPF) and lung cancer tissues." (PMID 38727265, 2024). "This revealed an overall increased deposition by AFs of collagen family members (COLs, including COL4A1 and COL11A1), fibrillins (FBN1 and 2) and tenascin (TNC), previously involved in lung fibrosis and deposited by CAFs in other cancers." (PMID 37938546, 2023). "Thus, both predicted direct targets CTGF and Col1a1 or un-predicted targets Col4a1 and α-SMA are down-regulated after miR-133a overexpression, strongly suggesting an anti-fibrotic role of miR-133a in pulmonary fibrosis." (PMID 31511493, 2019). "Furthermore, we show that DZNep treatment alone or in context of SARS‐CoV or SARS‐CoV‐2 infections reduces abundance of pulmonary fibrosis markers (e.g., SERPINE1, MMP14, and COL4A1) and increases levels of factors with antifibrotic activity (e.g., HOPX, PI3/ELAFIN, and SLPI)." (PMID 35833542, 2022). "The chronization of asthma and development of lung fibrosis was shown to either not affect observed asthma-driven upregulation of the genes, as in the case of Col1a1, Col4a1, and Col4a2, or downregulate the expression of Thbs2 and Tyrobp almost to the level of healthy control." (PMID 35625754, 2022).
cerebral aneurysms (7 papers, 2020 to 2024). "Individuals with a more severe MFS phenotype may have a second variant (pathogenic or of uncertain significance) in another MFS/thoracic aortic aneurysm/cerebral aneurysm gene, for example, COL4A1, as demonstrated in nine of 51 severely affected cases." (PMID 31950671, 2020).
coronary artery disease (7 papers, 2013 to 2024). "A study found that downregulation of COL4A1 in smooth muscle cells and endothelial cells increased apoptosis, impairing normal cardiac vascular function and increasing the risk of coronary heart disease." (PMID 38994496, 2024). "Moreover, genome‐wide association studies have correlated COL4A1 expression to coronary heart disease." (PMID 38576084, 2024). "The COL4A1 gene contains one of 27 SNPs associated with increased risk of coronary artery disease." (PMID 31721901, 2019). "These genes included Cdh13 and Lpl from Cluster 1; Nfia, Col4a1 and Serpinh1 from Cluster 2; Arhgef12, Col4a2, Scarb1 and Cst3 from Cluster 3; Pecam1 and Aldh2 from Cluster 4, providing plausible molecular basis for the inextricable causal link between age and coronary artery disease." (PMID 35615560, 2022). "However, the relationship between COL4A1 genetic polymorphisms and coronary artery disease (CAD) remains unclear." (PMID 24156251, 2013).
lung carcinoma (7 papers, 2009 to 2025). "We noticed that tip cells from RAECs and a breach EC phenotype in lung cancer shared similar expression patterns, including the upregulation of tip cell markers and collagen remodeling markers (COL4A1, COL4A2)." (PMID 38997406, 2024). "We concentrated on those genes that revealed a differential expression between IPF and lung cancer, such as higher expression of MMP1 and MMP3 in IPF than ADC, and lower expression of COL4A1 in IPF than in ADC." (PMID 33905434, 2021).